CCL21 (C-C motif chemokine ligand 21)
Diseases named in the same sentence as CCL21 in open-access papers (continued):
Sharing a sentence is not in itself a finding about the gene and the disease.
tumor (continued). "On this basis, Zhang's group used microfluidic system to further study the effect of CCL21-FA-UCNPs@mesoporous silica in simulating 3D tumor tissue." (PMID 33240857, 2020). "In comparison to controls and monotherapy, H&E staining of tumor sections revealed enhanced immune infiltrates with reduced tumor burden in the anti-PD-1 plus CCL21-DC tumor lysate vaccine treatment group." (PMID 32570793, 2020). "CCL21 is a potent chemoattractant for tumor-infiltrating lymphocytes, which can exert a robust anti-tumor immune response especially during the early stages of tumor progression." (PMID 32340161, 2020). "For instance, CCR7+ tumor cells will preferentially traffic toward CCL21 secreted by lymphatic endothelial cells (LECs), promoting initial metastasis through the lymphatic system." (PMID 32002106, 2020). "In a recent study, we demonstrated that CCL21-DC tumor lysate vaccine combined with anti-PD1 blockade led to tumor eradication in the Kras-G12Dp53null tumor model." (PMID 33167311, 2020). "Another alternative is to inject exaggerated CCL21-transduced DCs or fibroblasts that mediate the functional differentiation and recruitment of innate and adaptive immune cells into the tumor, which has been shown to destroy cancer cells." (PMID 32340161, 2020). "CCL21 is a chemokine that is present in humans and has an important role in mobilizing normal immune cells in response to tumor cells metastasizing to lymph nodes, via activation of a G protein-coupled receptor, CCR7." (PMID 31824269, 2019). "The mRNA levels of Ccr7, Mmp9, c-Fos (Fos proto-oncogene, AP-1 transcription factor subunit), c-Jun (Jun), Ccl19 (C-C motif Chemokine Ligand 19) and Ccl21 were significantly reduced in tumor of CRE treated mice." (PMID 30781353, 2019). "CCL21 plays a crucial role in the establishment of a tolerogenic tumor microenvironment by recruiting CCR7+ regulatory T cells in primary tumors and by promoting the formation of lymphoid like stromal structures with immunosuppressive features." (PMID 31024552, 2019). "For example, one study reported that high amounts of CCL21 recruit CD4+ LTi cells to tumors in a CCR7-dependent manner, which is associated with the formation of tumor-promoting lymphoid-like stroma in melanoma." (PMID 31507605, 2019). "CCL21 is also a potent chemoattractant in the tumor microenvironment, and its binding to podoplanin-expressing cancer-associated fibroblasts (CAFs) is involved in tumor immune escape." (PMID 30736372, 2019). "In this model, CCL21 was responsible for the establishment of a tolerogenic environment within the tumor bed via the recruitment of Tregs and MDSC." (PMID 31024531, 2019). "Pro-tumor: CCL21-mediated recruitment of ILC3 triggers CXCL13 secretion by TME stromal cells thereby enhancing tumor cell motility and promoting lymph node metastasis." (PMID 32117199, 2019). "Recent extension of these observations has shown a role for VEGF-C-induced CCL21 in the tumor infiltration of naive T cells prior to immunotherapy via CCR7-dependent chemotaxis." (PMID 31105685, 2019). "In a mouse model of breast cancer, it was also shown that CCL21 recruits CCR7-expressing ILC3s with an LTi phenotype (CD4+CCR6+) to the tumor environment." (PMID 31507605, 2019). "In this study, the effect of P. amarus-generated tumor lysate on the migration capacity of the DCs was investigated toward CCL21 LN-secreted chemokine." (PMID 30081891, 2018). "In preclinical studies, CCL21 combined with costimulatory molecules showed synergistic anti-tumor effects, increasing interferon-γ-producing CD8+ cells while inducing apoptosis in CD4+CD25+FoxP3+ regulatory T cells." (PMID 30209589, 2018). "Among them, C—C chemokine ligand 21, Secondary lymphoid tissue chemokine (CCL21), exerts antitumor immunity by co-localizing dendritic cells and T cells at the tumor sites." (PMID 29276695, 2018).
tumor (continued). "Direct in vivo testing indicated that CD8+ T-cells pre-cultured for 7 days on substrate-immobilized CCL21 + ICAM1 suppressed tumor growth to a significantly greater extent than T-cells cultured on unmodified substrates." (PMID 29942308, 2018). "We then checked the expression of the chemokine receptor CCR7 that binds to the lymphatic attracting chemokine CCL21 in tumor infiltrating OT1 T cells." (PMID 30258446, 2018). "An immunohistochemistry analysis of solid tumors revealed the expression of Exodus 2/CCL21 at the level of protein, both in tumor islets and stroma, strongly suggesting that tumor cells can be a source of chemokines in vivo." (PMID 30613350, 2018). "CCL21 is known to induce chemotaxis of mature DCs and naïve T cells, and groups have demonstrated improved anti-tumor responses following intra-tumoral introduction of CCL21 through transduced DCs in mouse models." (PMID 30209589, 2018). "VEGF-C also promotes the invasiveness of tumour cells in an autocrine manner and upregulates the production of CCL-21 by lymphatic vessels." (PMID 30406137, 2018). "In a triple-negative breast cancer model, CCL21 was sufficient to recruit RORγt+ innate lymphoid cells (ILCs) into the primary tumor and promote metastasis to LNs." (PMID 29527513, 2018). "CCR7 plays a role in the migration of tumor cells such as immune cells into lymphoid organs through binding to its only two ligands CCL19/CCL21." (PMID 30233771, 2018). "In the tumor microenvironment and in the secondary lymphoid organs, CCL21 chemokine is a potent and specific chemoattractant upon presentation on the surface of endothelial cells via glycosaminoglycans (GAGs)." (PMID 28416768, 2017). "This work demonstrates that tumor hypoxia, by modulating the expression of molecules such as PDPN, leads to easier liberation of tumor cells and, lowering the NK cells recruitment upon CCL21 presentation, it impairs the anti-tumor immune defence." (PMID 28416768, 2017). "Recently, the Boyden chamber incorporated into microfluidic systems were used to reconstitute the tumor-lymphatic microenvironment, in which luminal flow indirectly increases tumor cell (MDA-MB-231) transmigration by upregulating CCL21 expression." (PMID 28952543, 2017). "Irradiation down regulates DC chemoattractant CCL21 expression in tumor tissue, which reduces the retention of DCs in tumor area after irradiation." (PMID 28603525, 2017). "A PDPN expressing model of CAFs made it possible to demonstrate the same CCL21/CCR7 axis involvement in the tumor cells to CAFs recognition mechanism through PDPN binding of CCL21." (PMID 28416768, 2017). "One research in renal cell carcinoma found that local expression of CCL21 by tumor cells led to accumulation of mature dendritic cells and proliferating T-cells at the margin, exhibiting a local anti-tumor immune response." (PMID 27783999, 2017). "In accordance with their well-defined immunosuppressive role, the recruitment of Foxp3+ Tregs and myeloid derived suppressor cells (MDSCs) to TLSs within B16 melanomas engineered to express CCL21 led to promotion of tumor growth." (PMID 29312327, 2017). "In this manner, TGFβ appears capable of sensitizing both the tumor cell and the lymphatic endothelium to CCL21, so that it can signal and promote the chemotactic migration of the tumor cells towards the lymphatic vessels." (PMID 27367735, 2016). "In the tumor stroma, CCL21 has a unique ability to attract and educate naïve T cells in the regulatory chemokine environment." (PMID 28036019, 2016). "For example, CCL21 has been shown to attract circulating naïve T cells and DCs in tumors, and contribute to the control of tumor growth." (PMID 27752258, 2016). "This study showed that melanoma cells overexpressing chemokine CCL21 promotes attraction of Tregs, MDSCs and naïve T cells and induces lymphoid-like stroma, resulting in enhanced tumor growth." (PMID 28536374, 2016).
tumor (continued). "Patients with a good chemotherapeutic response had a higher CCL21 expression in the tumor sample compared to patients with a poor response." (PMID 27369431, 2016). "A mechanism of this targeted migration was traced to the capacity of TGF-β1 to promote CCR7/CCL21-mediated crosstalk between tumor cells and lymphatic endothelial cells." (PMID 25961925, 2016). "To show that the difference in expression between tumor samples and cell lines can be accounted for by infiltrating immune cells in the tumor tissues, we studied CCL21 expression at the protein level." (PMID 27369431, 2016). "TGF-β1 can promote CCR7/CCL21-mediated crosstalk between tumor cells and LECs, and increase CCR7 expression in EMT cells through p38 mitogen-activated protein kinase (MAPK)-mediated activation of the JunB transcription factor." (PMID 28036019, 2016). "For instance, B16F10 melanoma cells expressing the CCR7 ligand, CCL21, induced the formation of lymphoid tissues at the tumor site, recruited Tregs and myeloid-derived suppressor cells (MDSC) and promoted tumor growth." (PMID 26155419, 2015). "For example, if these were early cancers, perhaps CCL21 expression was upregulated in an attempt to mount an immune response then later diminished to ensure tumor survival." (PMID 24762633, 2014). "The requirement of both CD4 and CD8 T cell subsets for CCL21 mediated tumor inhibition was confirmed in CD4 and CD8 T cell knockout mice." (PMID 24810425, 2014). "Local expression of CCL21 by tumor tissue induced accumulation of mature DCs and proliferating T-cells at the tumor margin, reflecting a local anti-tumor immune response." (PMID 24810425, 2014). "A third study introduced CCL21 protein at the tumor site and found that these tumors had reduced angiogenic activity and increased T cell activation indicated by high IFN-γ, CXCL9, and CXCL10 levels." (PMID 24762633, 2014). "Overall, DC-CCL21 polymer treatment significantly reduced tumor burden, compared to control DC group or recombinant CCL21 injection group." (PMID 24810425, 2014). "The past 20 years of accumulated research evidence clearly indicates a fundamental role of CCL21 in anti-tumor immune activity." (PMID 24810425, 2014). "In accord with basic research, recent clinical observations also supported the anti-tumor role of CCL21." (PMID 24810425, 2014). "CCL21 is related to tumor tolerance by stimulating naïve T cells to which the presentation of TAAs will not be efficient due to the absence of co-stimulatory factors." (PMID 25505783, 2014). "In summary, these studies demonstrated that CCL21 has the capacity to recruit anti-tumor lymphocytes and APCs in tumor tissue, resulting in tumor regression or rejection." (PMID 24810425, 2014). "A single intratumoral injection of CCL21-vault nanoparticles was able to recruit anti-tumor effectors that induced potent anti-tumor activity and inhibit tumor growth." (PMID 24810425, 2014). "In a well characterized Lewis lung cancer model, CCL21-vault nanoparticles system showed effective anti-tumor efficacy." (PMID 24810425, 2014). "Currently, anti-tumor efficacy of polymer loaded with recombinant CCL21 is being further evaluated with combination of cisplatin chemotherapy and radiation therapy." (PMID 24810425, 2014). "In animal model of prostate cancer, local expression of CCL21 by cancer cells controlled by tet-on system enhanced lymphocytes infiltration, inhibited tumor growth and metastasis." (PMID 24810425, 2014). "The Dubinett and Sharma group first proposed and demonstrated that the establishment of CCL21 chemotactic gradient that favors localization of activated DC within the tumor is an effective strategy to restore antigen presentation." (PMID 24810425, 2014). "In this review, we discuss the anti-tumor efficacy of the chemotactic cytokine CCL21 and its pre-clinical and clinical application in cancer." (PMID 24810425, 2014).
tumor (continued). "The results of the studies of CCL21 on anti-tumor immunity suggest that interaction between tumor released CCL21 and host immune response is complex." (PMID 24810425, 2014). "Injection of CCL21 also generated systemic immune response, because splenic lymphocytes from CCL21 treated tumor-bearing mice demonstrated enhanced cytolysis against autologous tumors." (PMID 24810425, 2014). "The role of CCL21/CCR7 axis in tumor immunity has been closely investigated in the past two decades." (PMID 24810425, 2014). "Local expression of CCL21 by cancer cells also reduced tumor growth in nude mice, probably through inhibition of neoangiogenesis." (PMID 24810425, 2014). "Preclinical findings suggest that improved anti-tumor efficacy of CCL21 treatment can be achieved by combining with radiation, chemotherapy or targeted therapy regimens." (PMID 24810425, 2014). "Their data again showed better tumor eradication and tumor-protective immunity in the mouse cohort receiving CCL21-expressing DCs intratumorally." (PMID 24967094, 2013). "In contrast, other studies indicate that the CCL21/CCR7 pathway promotes increased tumor control as a result of increased recruitment of effector immune cells." (PMID 23874342, 2013). "S. Typhimurium has been used in several murine trials examining immunotherapies, with significant tumour reduction resulting from local bacterial expression or tumour cell expression of the immune-stimulating molecules IL-18, CCL21, LIGHT or Fas ligand." (PMID 23537317, 2013). "Ectopic delivery of LTα/β or LIGHT (aka TNFSF-14 or CD258) promotes PNAd+ HEV, CCL19/CCL21 production, massive naïve T cell infiltration, and (tumor-specific) cross-priming in the context of TLO structures." (PMID 24348473, 2013). "The superiority of DC.CCL21 in enhancing the cross-priming of protective Type-1 anti-tumor T cell responses has also been confirmed in alternate murine models." (PMID 24348473, 2013). "For example in this review, combinatory treatments between vaccines and IL-12, GM-CSF, CCL21, or β-defensins markedly increased the immune response toward tumor endothelial cells." (PMID 21385454, 2011). "It is proposed that by altering the tumor microenvironment, CCL21-secreting tumors shift the host immune response from immunogenic to tolerogenic, which facilitates tumor progression." (PMID 24212647, 2011). "In comparison to controls, CCL21-vault treatment resulted in extensive tumor T and DC leukocytic infiltrates." (PMID 21559281, 2011). "Although the survivin-CCL21 vaccine group markedly inhibited tumor angiogenesis, it is of interest that angiogenesis of wound healing and fertility were unaffected." (PMID 21385454, 2011). "A single intratumoral injection of CCL21-vaults led to significant inhibition in tumor growth compared to controls." (PMID 21559281, 2011). "To this end we evaluated CCL21-vault nanocapsules as an “off the shelf” therapeutic platform against tumor growth in vivo utilizing the well characterized 3LL cancer model." (PMID 21559281, 2011). "Our rationale for administration of intratumoral CCL21-vault nanocapsules is to promote the recruitment of T lymphocytes and DC into the tumor microenvironment for a robust antitumor activity." (PMID 21559281, 2011). "CCL21-vaults induced systemic antitumor responses by augmenting splenic T cell lytic activity against parental tumor cells." (PMID 21559281, 2011). "Our findings indicate that a single intratumoral administration of CCL21-vault nanocapsules recruits antitumor effectors, induces potent antitumor activity and inhibits tumor growth." (PMID 21559281, 2011). "Exploring possible mechanisms in cell-based systems revealed unique and critical roles served by lymphatic endothelial HS in mediating lymphatic-directed tumor cell migration in response to the chemokine CCL21." (PMID 21172016, 2010).
tumor (continued). "More importantly, their respective ligands, CXCL12 and CCL21, exhibited significant differences in expression between primary tumor and lymph node metastasis tumor (P = 0.016 and P = 0.004)." (PMID 20181250, 2010). "Importantly, we questioned whether these signaling alterations on tumor cells that depend on the state of HS in the conditioned medium were associated with "upstream" alterations in the ability of CCL21 to associate with CCR7 G-protein coupled receptors on tumor cells." (PMID 21172016, 2010). "Lymphatic heparan sulfate was also required for binding of CCL21 to its receptor CCR7 on tumor cells as well as the activation of migration signaling pathways in tumor cells exposed to lymphatic conditioned medium." (PMID 21172016, 2010). "In vivo depletion of MIG, IP-10, or IFN-γ individually or in combination reduced the anti-tumor efficacy of CCL21-DC." (PMID 18644162, 2008). "The capacity of mice immunized with CCL21-DC to reject a secondary challenge with tumor cells demonstrates that CCL21-DC effectively generate a systemic CTL response and enhance tumor immunogenicity." (PMID 18644162, 2008). "Altogether the in vitro data in human DC support our previous findings from murine models in which intratumoral injection of CCL21-DC led to the increased production of IFN-inducible chemokines and cytokines associated with tumor regression." (PMID 18644162, 2008). "These experiments confirmed the immature phenotype of CCL21-DC as well as their capacity to endocytose antigen, which has been suggested to be fundamental in the initiation of tumor-specific immune responses." (PMID 18644162, 2008). "To probe functionality of initial lymphatic vasculature within the tumor, we measured the expression of CCL21, a lymphatic endothelium-specific cytokine that attracts antigen-presenting cells, T-lymphocytes, and conversely metastatic cancer cells through CCR7 activation." (PMID 39998766, 2025). "Moreover, CCR7 facilitates lymph node metastasis by guiding tumor cell migration toward CCL21-expressing microenvironments and recruiting immunosuppressive Treg cells." (PMID 41462979, 2025). "Likewise, CCL21 protein content in tumor-draining axillary lymph nodes correlated with gene expression data from the viable tumor region." (PMID 39998766, 2025). "The increased CCL21 production within aCD40-treated tumors may serve to retain these regulatory DCs within the tumor microenvironment, thereby facilitating more effective T cell priming in TDLNs." (PMID 40585246, 2025). "It was hypothesized that the tumor-mediated impairment of T-cell function could lead to a decreased anti-tumor response from CCL21-DC." (PMID 40006675, 2025). "Finally, VPs fused with the chemokine CCL21 or tumor antigens like NY-ESO-1 have been shown to trigger immune responses in cancer models, resulting in the suppression of tumor growth." (PMID 40004027, 2025). "Additionally, experiments using engineered CAR-T cells co-expressing IL-7 and CCL21 demonstrated enhanced anti-tumor efficacy, attributed to the increased survival and infiltration of both CAR-T cells and DCs." (PMID 39861713, 2025). "Additional chemokines implicated in TLS development include CCL19 and CCL21, predominantly produced by DCs and HEV endothelial cells; their upregulation in tumor-associated TLS has prompted interest in their use as biomarkers and as targets for therapeutic interventions." (PMID 41374956, 2025). "However, CCL21 expression from lymphatic endothelial cells must be defined to distinguish lymphatic-specific contributions from those of macrophages and the tumor cells themselves." (PMID 39998766, 2025). "Likewise, lymphatic vascular remodeling shows the potential for an inflammatory phenotypic shift through CCL21 gene expression in the tumor, and LYVE−1 immunofluorescent staining within the TDLN." (PMID 39998766, 2025).